CD4 (CD4 molecule)
Diseases named in the same sentence as CD4 in open-access papers (continued):
Sharing a sentence is not in itself a finding about the gene and the disease.
infection (continued). "IFN-γ is produced by activated CD8-positive T cells, NK cells and CD4-positive T cells and serves as an important immune regulator to protect against infection and tumors." (PMID 37039042, 2023). "We analyzed IL-17A expressing CD4+ T cells in the lung at 6 and 21 days after infection by intracellular cytokine staining following in vitro stimulation with heat-killed P1121, T4 and a gram-negative bacterium, H. influenzae strain NT127." (PMID 37222516, 2023). "In lymphocytes, the course of infection is characterized by an initial decrease in CD4 T-cell number and function." (PMID 37345053, 2023). "MTB is an intracellular pathogen whose infection is mainly controlled by the immune responses induced by T helper 1 (Th1) CD4+ T cells secreting cytokines, such as IFN-γ." (PMID 36977141, 2023). "Our results indicate that SARS-CoV-2 spike–reactive CD4+ T cells are transiently lower under dexamethasone treatment and up to 3 months after infection." (PMID 36881474, 2023). "Lung CD4+ T cells displayed significantly increased Th1 (IFNγ) and Th2 (IL-4, IL-5, IL-13) cytokine production potential during pre-patent infection at the higher dose." (PMID 37012228, 2023). "Next, we studied the Acute cohort and investigated the impact on CD4 T cells in different CNS compartments during the acute phase of infection." (PMID 38060615, 2023). "Our knowledge of the role of CD4+ T cells in the control of M. tuberculosis infection, in the peripheral blood as well as at the site of infection, is still incomplete." (PMID 38140266, 2023). "PR8-OVA infection induced a robust population of donor PD-1+CXCR5+CD4+ T cells in the spleen as well, although the overall OT-II cell response was stronger in the draining medLN than in the spleen." (PMID 37330549, 2023). "In infection-mediated inflammatory response, CD4+ T lymphocytes, that appear to be the main producers of enkephalins of immune origin, play a pivotal role in the endogenous regulation of inflammatory pain in mice." (PMID 37968381, 2023). "WT mice also display increased FoxP3+ cell frequencies amongst CXCR5+CD44+CD4+ T cell populations one week post infection compared to μMT animals, suggesting B cells promote TReg development amongst CXCR5+CD44+CD4+ T cells during Brucella infection." (PMID 37721965, 2023). "The breakthrough infections were equally distributed between cellular hypo-responders and responders for both CD4 + and CD8 + T cells." (PMID 37095240, 2023). "Mtb-specific CD4 T cells in the blood were tracked throughout the infections via the monitoring of the IFN-γ responses that followed PBMC stimulation with dominant peptides." (PMID 37039646, 2023). "Remarkably, HIV-1 trans-infection mediated by APCs is 10 to 1000-fold more efficient at infecting CD4+ T cells compared to cis-infection in vitro, and trans-infection can shield HIV-1 from immune surveillance, neutralizing antibodies, and ART." (PMID 38140588, 2023). "The increased influx of macrophages to the site of infection was in agreement with the robust Th1 response and CD4+IFNγ+-producing cells, which function as major macrophage activators, detected in anti-Gr1-treated mice." (PMID 36776848, 2023). "These HIV-1-EVs control infection of recipient T cells through CD4-independent clathrin-mediated endocytosis." (PMID 36674550, 2023). "Among these responding cell populations, monocytes were the strongest responders to infection, followed by CD4+ T central memory, NK, and CD8+ T cells." (PMID 38020713, 2023). "Advanced immune suppression (CD4 count < 350 cells/μl) among newly diagnosed long-term infection were significantly higher compared to those who were recently infected which accounted 47.8% (95%CI = 33.2–52.1) and 30.9% (95%CI = 21.3–32.2), respectively." (PMID 36653851, 2023). "We found antigen-specific CD4+ T cells from each of 9 distinct transcriptional profiles in both vaccinated and infected subjects 3–6 months after infection." (PMID 37790414, 2023).
infection (continued). "To understand the association between SHIV-specific Th1 cells and protection in this study, we stratified vaccinated animals into two groups (low vs high) based on median IFNγ + CD4 T cell response and compared the rate of infection." (PMID 37553348, 2023). "Blocking CD18 with specific antibodies significantly reduced the infection of MDMs by fusion with infected T cells using either Jurkat or primary autologous CD4+ T cells." (PMID 36988579, 2023). "The mean CD4+ T cell viability was 86.92% (range 78.00%–93.00%) 6 hours, 95.25% (92.50%–97.00%) 24 hours, and 91.76% (84.50%–98.58%) 48 hours after infection." (PMID 37079384, 2023). "These three features have both local and systemic consequences, leading to lifelong infection, irreversible CD4+ T lymphocyte depletion and dysfunction, and immune senescence and exhaustion." (PMID 37110276, 2023). "We further found that the predominance of productive infection in resting CD4+ T cells reflects target cell availability." (PMID 37733443, 2023). "Transcriptome profiles of IL-25- and IL-33-treated pulmonary effector CD4+ T cells were analyzed by comparing upregulated genes in Il17rb−/− mice and wild-type mice during infection." (PMID 37337050, 2023). "This was exemplified by a recent study among age range 18-82 years in which it was found that the frequency of infection-induced CD4+ T cells significantly drop with lower age." (PMID 38193077, 2023). "In experimental models of cutaneous leishmaniasis (CL), the immune response is inhibited at the infection site by IL-10-secreting CD4+ T cells in C57BL/6 (Th1-dominant response) or BALB/c (Th2-dominant response) mouse models." (PMID 37235324, 2023). "Depletion of CD4+ T cells, IL-10, or IL-4 before infection or vaccination ameliorated disease severity but consequently resulted in prolonged viral shedding." (PMID 37896776, 2023). "As expected, CD4+ T cells pretreated with IL-15 had a higher percentage of infection by a CCR5-tropic HIV-1 reporter virus." (PMID 36821374, 2023). "GrB is expressed primarily by activated memory CD8 + and memory CD4 + T cells and NK cells during infections and inflammation." (PMID 38072840, 2023). "The reinfection experiments were performed after CD4+ T lymphocyte depletion using the same dose and timeframe of infection as in the primary infection model which had yielded 100% placental transmission." (PMID 37796819, 2023). "In contrast, natural infection and wPV immunization elicit Th1/17 polarized systemic responses and elicit CD4+ TRM and mucosal antibodies upon challenge with B. pertussis." (PMID 37275891, 2023). "CD4 T cells increased their instantaneous speeds and turning angles between 6.5 and 7 days post-infection (v ̄ = 7.92μm/min versusv ̄ = 9.49μm/min andθ ̄ = 65.7° versusθ ̄ = 69.8°, respectively)." (PMID 37811200, 2023). "Beyond functioning in exocytic release and cell-cell spread to other immune cell types including CD4 + T Cells, these vesicular sites are also thought to function as reservoirs of infection within macrophages." (PMID 37454116, 2023). "A CD4+ T-helper cell-mediated immunopathological response triggered by exposure to AAV2 infection is highly probable, consistent with the markedly increased frequency of the MHC class II HLA-DRB1*04:01 allele in affected children." (PMID 36996873, 2023). "The frequency of HLA-DR+CD38+CD4+ T cells significantly increased after breakthrough infection compared to that before infection in heterologous booster individuals." (PMID 38140668, 2023). "Our results show that this MTE vaccine activates CD4+ T and CD8+ T cell responses and protects the mice from lethal infection by SARS-CoV-2 and its variants." (PMID 37033973, 2023). "Using IFNγ ELISpot and flow cytometry, we compared virus-specific CD4+ and CD8+ T-cell responses over 18 months post-infection with ancestral, alpha or delta SARS-CoV-2 variants and demonstrated that CD8+ TSCM is a relevant marker of long-term protection." (PMID 37046496, 2023).
infection (continued). "Recent studies have shown that Ly6Chi monocytes surround S. Typhimurium-confining granulomas in the spleen and recruit CD4+ T cells to the foci of infection by producing CXCL9 and CXCL10, both are ligands for CXCR3 expressed by Th1 cells." (PMID 37733817, 2023). "The loss of Vδ2 T-cells during untreated HIV disease correlates strongly with CD4+ counts and viral load and occurs quickly after infection." (PMID 37376629, 2023). "The DEFI group found that infection-only patients had low switched memory B cell counts, while decreased naïve CD4+ T-cell counts and increased CD4 + CD95+ cells were associated with lymphoid proliferation, autoimmune cytopenias, or chronic enteropathy." (PMID 37435172, 2023). "In the case of human immunodeficiency virus (HIV), Gal-3 interacts with the viral envelope glycoprotein gp120, enhancing its binding to host cell surface receptors, such as CD4, and subsequently enhancing infection." (PMID 37298569, 2023). "The infection-induced CD4 effectors required signals from autocrine IL-2 to effectively differentiate into long-lived CD4 memory." (PMID 38152398, 2023). "Infection with HIV damages CD4 + T cells, which are the most essential components of the immune system." (PMID 37156899, 2023). "We have previously reported that MDSC expand during S. aureus infection and exert a suppressive effect of CD4+ T cells that support infection chronicity." (PMID 37480485, 2023). "In the early stages of HIV and SIV (simian immunodeficiency virus) infection, viral replication in the intestinal region is extremely high, and most of the CD4 + T cell population in the gut is depleted due to toxicity from infection or immune responses." (PMID 37202790, 2023). "As a result, we were unable to match the three groups of patients for several important characteristics such as year of infection, time between samples, and CD4 count." (PMID 37333388, 2023). "Lung CD8+ T cells producing IFNγ following ex vivo antigen stimulation were also found in vaccinated mice 10d post infection, albeit in considerably lower numbers compared to what was observed with CD4+ T cells." (PMID 36732332, 2023). "Here, we analyzed the efficiency with which HIV-1 and HIV-2 primary isolates are able to interact with Mø, DCs, and CD4+ T lymphocytes in either cis- or trans-infection." (PMID 37243118, 2023). "At 14 days post-infection, lungs of WildR mice had lower absolute counts of CD4 and CD8 T cells than LabC mice and these differences faded to undetectable levels at later time points." (PMID 37494371, 2023). "At five days after CD4+ T cell transfer, respiratory rate was significantly reduced in the C-IRIS group compared with the three control cohorts (naive Rag1−/− mice, Rag1−/− mice with CnH99 infection alone, and Rag1−/− mice with CD4+ T cell transfer alone)." (PMID 37380639, 2023). "We believe HIV controllers maintain high CD4 + T cell counts partly because their T cells have significantly reduced CCR5 expression which protects them from infection and depletion." (PMID 37231494, 2023). "To investigate the functionality of spike-specific CD4+ T cells after natural infection and subsequent vaccination, we measured the intracellular production of IFN-γ, IL-2, and tumor necrosis factor (TNF) in response to peptide stimulation." (PMID 38064569, 2023). "The production of IFN-γ was also a prominent feature of the CD4+ T-cell phenotypes mobilized during the infection." (PMID 37936699, 2023). "Although their main task is to provide help to other effector immune cells, a growing number of infections and cancer entities have been described in which CD4+ T cells exhibit direct effector functions against infected or transformed cells." (PMID 37965314, 2023). "Because the antigen-specific CD8+ T cell response develops more slowly than the CD4+ T cell response after natural infection and primary vaccination, it reaches its maximum only after administration of the second vaccine dose." (PMID 37020560, 2023).
infection (continued). "Our findings provide an atlas of human antigen-specific CD4+ T cell transcriptional phenotypes in the dLN and blood following vaccination or infection." (PMID 37790414, 2023). "Previously, our lab has found that CD4 memory T cells become quiescent during the contraction phase of infections, a necessary requirement for their long-term survival." (PMID 37908352, 2023). "Before addressing these, we investigate potential subtype differences in the CD4+ T cell decline, set-point viral load and CD4+ T cell level after primary infection." (PMID 37161335, 2023). "In DCs, by budding at the tip of filopodia, HIV-1 can tether several neighboring CD4+ T cells, leading to viral transfer and infection of the targeted T cells." (PMID 37685911, 2023). "Mucosal cellular and humoral adaptive immune responses against respiratory pathogens are critical to clear infections from the respiratory tract and studies in murine models showed that CD4+ T cells are necessary for clearing natural B. pertussis infections." (PMID 37275891, 2023). "We observed increasing mb-TLR2 expression in NK cells and decreasing CD4+ T cells in the jejunum following infection." (PMID 38140264, 2023). "In primate lentiviruses (PLVs), including HIV-1, the viral envelope protein binds to two host receptor proteins, the CD4 protein (major receptor) and chemokine receptors (coreceptors), to initiate infection." (PMID 37724881, 2023). "This leads to an increase in IFN-γ production by CD4+T cells, which in turn enhances the wound healing process during the infection." (PMID 37111420, 2023). "A study using a toxoplasma vaccine strain in an infection model demonstrated that both CD4+ T cells and CD8+ T cells were important for controlling the T. gondii infection." (PMID 37235437, 2023). "Crucially, this quiescence state of CD4 memory T cells is mediated by B cells during the clearance of infection, when antigen reaches to lower than stimulatory levels." (PMID 37908352, 2023). "During the adaptive immune response against Mycobacterium tuberculosis (Mtb), millions of CD4 T cells traffic to the site of infection, but relatively few find antigen and become activated to carry out effector functions." (PMID 38110410, 2023). "Our findings imply that reduced CD4+-T-cell numbers and infections are common in patients with RRMM." (PMID 37152008, 2023). "Infection with Salmonella Enteritidis in laying hens has been shown to increase the numbers of both CD4+ and CD8+ T cells along with macrophages in the ovaries and oviduct around 7–14 days post-inoculation, which was followed by peak upregulation in B cells." (PMID 38004824, 2023). "Kaplan–Meier analysis was used to further explore the effect of CD4+ T-cell counts of <300/μL on the overall probability of early infection." (PMID 37360336, 2023). "Higher baseline CD4 counts were associated with lower HIV DNA levels before (r = −0.5049, p = 0.0012) and after breakthrough infection (r = −0.4544, p = 0.0042)." (PMID 38140668, 2023). "Flow cytometry analysis of Tex subpopulations at day 90 of infection further confirmed the predominance of TIM-3+ cells within both CD4+ and CD8+ T-cell compartments in the lesion sites, compared to their respective CXCR5+ and CXCR5+TIM-3+ cells." (PMID 37691941, 2023). "In summary, CD57+ CD4+ T cells expand in response to several different types of infection, and CD57 marks cells that have become dysfunctional in response to antigenic stimulation." (PMID 37161048, 2023). "Our finding that galectin deficiency leads to slight impairments in both autophagy and antigen-specific CD4 T cell activation raises the possibility that these phenotypes could be linked and suggests how an autophagy phenotype might manifest during later stages of infection." (PMID 37352334, 2023). "The magnitude of early CD4+ T cell immune responses correlate with the severity of initial infection; thus, it can be used as a tracker of PC19S severity." (PMID 36851746, 2023).
infection (continued). "The absence of CD4+ T cells will lead to the proliferation of CD8+ T cells, and CD8+ T cells compensate and defend CD4+-depleted hosts from an otherwise fatal infection." (PMID 37251371, 2023). "Viremia decreased between 2 and 4 wpi despite no detectable serum NA in the pigs from the MLV vaccinated gilts again demonstrating the central role of cell-mediated immunity (CD4+ T cells and CTLs) in recovery from infection." (PMID 36992179, 2023). "In these mice, HIV induced a decrease in the CD4+ T cells two weeks after infection, which correlated with an increase in p24 levels in plasma." (PMID 36680271, 2023). "Only naive CD4+ T cells appeared to be reduced during the first week of infection in long-term carriers." (PMID 37529320, 2023). "To some extent, nadir CD4 counts at enrollment reflect the duration of infection, and we included baseline CD4 counts in this study." (PMID 38124745, 2023). "We therefore investigated the dynamics of HIV-induced lymphocyte death by infection of an MT2 CD4+ T cell line with HIV strain IIIB." (PMID 36911666, 2023). "We concluded that, in order to survive and become memory cells, CD4 effectors generated by infection must again receive signals from cognate recognition and costimulation, resulting in autocrine IL-2, to which they respond and become memory." (PMID 38152398, 2023). "In contrast to humoral responses to BNT162b2, SARS-CoV-2-specific CD4+ T-cell proliferative responses were similar in infection-naïve individuals compared to previously infected individuals after a single dose of vaccine." (PMID 37942333, 2023). "We then quantified the surface density of HIV-Gag(i)GFP platforms 48 h post infection at the cell membrane of infected Jurkat CD4 + T cells." (PMID 37907528, 2023). "Rhesus macaques immunized with VACV were demonstrated to mount a defensive antibody response against deadly MPOX infection, but this was found to be highly dependent on the amount of CD4+ T cells." (PMID 37533932, 2023). "This is in line with the median time until ART initiation from estimated time since infection, which is decreasing over the observation time, while median CD4 T-cell count at ART initiation is increasing over observation time." (PMID 37257071, 2023). "In this study, for activated and memory CD4 + T cells, we also used an R5 tropic reporter virus for infection, as this subtype has more in vivo relevance in the mucosal area." (PMID 37202790, 2023). "PLHIV commonly exhibits a progressive decline in intestinal CD4+ T cells, with a preferential absence and significant depletion of Th17 cells, throughout infection." (PMID 37608956, 2023). "CD4+ T central memory cells showed a high frequency in PBMCs at 1 dpi post‐Alpha or ‐Beta infection." (PMID 38020713, 2023). "For example, CD4+ CTL are known to mediated liver disease upon secondary infections with dengue virus." (PMID 37965314, 2023). "During both CEV genogroups infections, the expression levels of most of the genes for T cell response, including CD4, CD8b1, and GzmA were down-regulated in AS and koi at all time points compared to day 0 control." (PMID 37465154, 2023). "In agreement, ex vivo exposure of CD4+ T cells with SARS-CoV-2 resulted in 10% reduction of cell viability 24 hr after infection with a low MOI (0.1)." (PMID 37523305, 2023). "The CD4+ and CD8+ T-cell subsets that participate in cellular immunity carry out distinct roles in combating infections caused by Eimeria parasites." (PMID 38093398, 2023). "A recent report assigned this protective effect to CD4+ T cells which was mostly evident in the first 2 weeks of infection." (PMID 37388738, 2023). "For assessing the requirement for CD4+ T cells during primary infection, MHC-II deficient mice (I-A-/-I-Enull), which lack functional CD4+ T cells, were i.v. infected with TAS2010." (PMID 37733817, 2023).